SOCS1 (suppressor of cytokine signaling 1)
Diseases named in the same sentence as SOCS1 in open-access papers (continued):
Sharing a sentence is not in itself a finding about the gene and the disease.
tumor (continued). "Most recently, upregulation of the microRNA miR148-a in tumor-associated DC was shown to impair TLR-mediated maturation by suppressing expression of the DNA methyltransferase DNMT1, which in turn led to hypomethylation of the Socs1 gene and upregulation of the SOCS1 TLR signaling suppressor." (PMID 29209327, 2017). "However, SOCS1 in DCs and likely T cells suppress anti-tumor immunity; therefore, silencing SOCS1 in these cells could also be therapeutic." (PMID 29312162, 2017). "Therefore, blocking of SOCS-1 expression in adoptive transferred NK cells or T cells could further enhance anti-tumour potency of this form of therapy." (PMID 27713158, 2016). "Furthermore, 6 oncogenes and one known tumor suppressor, SOCS1, are predicted to be miRNA targets." (PMID 23741392, 2013). "However, also silencing of SOCS1 has been described in various tumour types." (PMID 24058673, 2013). "In addition, the spread of mutations over the coding region sustains the hypothesis that SOCS1 is a tumor suppressor." (PMID 23296022, 2013). "SOCS1 not was associated with the Gleason score, tumor stage, age of the patient, or the PSA level." (PMID 23231923, 2012). "Moreover, restoration of SOCS-1 suppresses tumour growth in HCC and haematopoietic malignancy." (PMID 15354212, 2004). "Meanwhile, hsa-miR-8060 and hsa-miR-4458 suppress SOCS1, affecting JAK/STAT and NF-κB signaling, thereby promoting tumor proliferation and immune evasion." (PMID 40076502, 2025). "In the GBM TME, dysregulated SOCS1 and SOCS3 expression suppress anti-tumor immune responses by impairing CD8+ T cell and NK cell function." (PMID 40076502, 2025). "Previous studies have shown that co-alterations of JAK3 and SOCS1 amplify downstream STAT signaling and enhance tumor cell survival." (PMID 41008827, 2025). "Decreasing in proliferation, invasion, migration, and EMT of MDA-MB-231 and A375 cancer cells in vitro and BC tumor size in vivo.↓ mRNA stability of PPARG, CEBPA, and CEBPB.↑ mRNA stability of SOCS1.↑ drug sensitivity." (PMID 41157107, 2025). "In AD, one study reported that it acts as an oncogene by suppressing SOCS1 and PTEN tumor suppressors, leading to activated JAK/STAT and PI3K signaling pathways that drive tumor growth and correlate with poor patient outcomes." (PMID 41465462, 2025). "The analysis revealed that the expression of SOCS1 and most immune checkpoints positively correlates with stromal, immune, and ESTIMATE scores, while inversely correlating with tumor purity." (PMID 39654174, 2024). "Of note, in vitro and in vivo studies conducted on SCC models showed that SOCS3 (and SOCS1) forced expression by SOCS3-derived peptide (KIR-ESS, see paragraph 4.1) efficiently suppresses IL-22-induced tumor growth." (PMID 38975347, 2024). "miR-922, which has been found to be overexpressed in GC, targets the SOCS1 gene and negatively regulates its expression by activating the JAK and AKT pathways, promoting tumor cell proliferation and motility." (PMID 38455038, 2024). "As for SOCS1, aberrant expression of SOCS3 has been observed in certain cancers, influencing the tumor microenvironment and immune responses." (PMID 38975347, 2024). "Suppressor of cytokine signaling 1 (SOCS1) is a potent regulator immune cell responses and a proven tumor suppressor." (PMID 38415248, 2024). "Twenty genes that were commonly upregulated by NTX-301 in the three different CCLs were involved in immune activation, and these genes included known tumor suppressors such as BTG2, ALOX5, SOCS1, and TP53INP1." (PMID 36980623, 2023). "Spatial CRISPR screening confirmed tumor-facilitating effects of immune checkpoints (PD-L1 and CD47), and also identifies tumor composition, organization, and immune infiltration in the TME, following Socs1 and TGFBR2 KO lesion." (PMID 36797756, 2023). "CGP of PCL tissues revealed the tumor to be wildtype for CD79B, MYD88, CARD11, and TNFAIP3, with genomic alterations detected in SMO, CIITA, ETS1, HST1H1D, and SOCS1." (PMID 36342081, 2023).
tumor (continued). "In assessing the impact of SOCS1 and PD-1 inactivation in transferred CD8+ T cells on the cellular composition of tumor, we observed depletion of Foxp3+ Tregs relative to sgOlf OT1s in mice treated with sgSocs1 OT1s, but not sgPD-1 OT1–treated animals." (PMID 38099496, 2023). "This suggests the existence of tumor cells that survive the initial exposure to CDDP and overexpress SOCS1 in response to the insult as another possible source of CDDP-DTP cells." (PMID 37916165, 2023). "In contrast, the expressions of SOCS1, EPS15, GLI3, NR2F2, and RCOR1 were significantly decreased in tumor compared to normal tissue (p < 0.05)." (PMID 37916165, 2023). "In conclusion, our findings uncovered that CASC2 could act as a tumor suppressor gene and inhibit cell proliferation, migration, and invasion through binding to miR-155, thus increasing the expression of its target gene SOCS1, demonstrating the ceRNA function of CASC2." (PMID 36816357, 2023). "As cytokines and growth factors that facilitate physiological hepatocyte proliferation also drive hepatocarcinogenesis, SOCS1 and SOCS3 likely mediate their tumor suppressor functions, at least partly, via attenuating HGF and IL-6 signaling, respectively." (PMID 36765862, 2023). "The immunohistochemistry staining of ccRCC tissues from tumor samples from patients in hospital cohort 2 also revealed expression of RNF7 and SOCS1." (PMID 35562668, 2022). "SOCS1 (suppressor of cytokine signaling 1) is involved in the negative regulation of cytokines that act via the JAK/STAT pathway and it is also known as a tumor suppressor and M1 marker." (PMID 35742830, 2022). "Atypical SOCS1 and SOCS3 expression in established tumor cell lines and also at advanced clinical stages of cancer is considerably variable." (PMID 35844493, 2022). "Other deregulated miRNAs also serve as modulators of tumor-related signaling pathways, such as miR-340 in Ras/Raf/MAPK and let-7b in SOCS1/STAT." (PMID 34646772, 2021). "Tanemura at al. demonstrated that during tumor progression, several tumor-related genes and loci, including WIF1, SOCS1, RASSF1A, TFPI2, MINT17, and MINT31, gain methylation with advancing stages." (PMID 34575678, 2021). "In xenograft tumor tissues, the SCC-9-derived exosomes group exhibits highly expressed miR-29a-3p, lowly expressed SOCS1, and highly expressed p-STAT6." (PMID 34722637, 2021). "Suppressor of cytokine signaling 1 (Socs-1) plays a role in negative regulation of the Jak-Stat pathway, IFN-γ secretion, anti-tumor immunity, and infection immunity." (PMID 32727064, 2020). "The downregulation of SOCS1 in BMDC further led to a drastic enhancement in cytokine production, and finally resulted in the essential induction of anti-tumor immune response." (PMID 31903120, 2020). "Phenomenon was shown in melanoma where highly expressed exosomal miR-155 inhibits the expression of SOCS1, activates the JAK2/STAT3 pathway, up-regulates the expression of FGF2, VEGFA and MMP9 in CAFs, and promotes the formation of blood vessels in the tumor." (PMID 32299469, 2020). "Up-regulated exosomal miR-let-7i in tumor-derived exosomes (TEX) can be taken up by mDCs, resulting in changes in intracellular levels of IL-6, IL-17, IL-1b, TGFbeta, SOCS1, KLRK1, IFNγ, and TLR4, thereby suppressing the immune response." (PMID 32299469, 2020). "Tumor tissue lysates of the CT26Flag−CAGE1 cells showed the interaction of FcεRIβ with HDAC3 and SOCS1." (PMID 31799196, 2019). "Conversely, restoring IFN-β expression in OSM-expressing TNBC cells restored the expression of select ISGs (including STAT1, STAT2, IRF9, SOCS1, MX1, and OAS1 and reduced tumor sphere formation and tumor-initiating capacity." (PMID 31036052, 2019). "In this way, SOCS1 and SOCS3 also act as fail-safe tumor suppressors in response to aberrant JAK/STAT signaling." (PMID 31557897, 2019).
tumor (continued). "The suppressor of cytokine signaling 1 (SOCS1) was recently shown, in HCC lines, to regulate the HGF signal; SOCS1 inhibited the HGF-induced MET-mediated cell growth/proliferation, the invasion of the extracellular matrix, and the dissemination of tumor cells." (PMID 31781608, 2019). "By comparing with the adjacent non-tumor tissue samples, 24 ATC specimens were found to have lower SOCS1 protein expression." (PMID 31718618, 2019). "The tumor tissue lysates of CT26Flag−CAGE1 cells revealed the activation of mast cells based on the induction of interactions of FcεRIβ with HDAC3 and SOCS1." (PMID 31799196, 2019). "Together, SOCS-1 and SOCS-3 play important roles as tumor suppressors by negatively regulating the activation of STATs." (PMID 30987235, 2019). "For example, condition medium derived from tumor cells increased the expression of several transcription factors in MC that influence allergic inflammation, such as Histone deacetylase-3 (HDAC3), SOCS1, and SNAIL, as well as increasing MC degranulation." (PMID 31052286, 2019). "Very consistently, there are elevated anti-tumor molecules such as perforin, granzyme B, CTSE and increased Th1 transcription factor T-bet while decrease of Th1 inhibitory molecule like SOCS1 and Twist1 in the lung of CD4-Chi3l1 KO mice." (PMID 29403003, 2018). "In detail, miR-155 overexpression and silence of its target SOCS1 in CD8+ T cells enhanced the antitumor response and augmented tumor destruction." (PMID 30619765, 2018). "SOCS1 and SOCS3 are important regulators of tumor-infiltrated T cell, dendritic cells (DCs), myeloid-derived suppressor cells (MDSCs), and macrophages." (PMID 28228755, 2017). "Similar to SOCS1, the expression and function of SOCS3 vary significantly among different tumor types." (PMID 28228755, 2017). "SOCS1-KIR also prevented antigen from increasing the expression of SOCS1, HDAC3 and TGaseII and also prevented antigen from inducing an interaction of FcεRIβ with HDAC3 and Lyn in tumor tissue." (PMID 28968979, 2017). "While there is no consensus on a gene panel to determine the CIMP status of a tumour, one of the most commonly used is the Weisenberger panel of genes comprising of CACNA1G, NEUROG1, RUNX3, SOCS1 and IGF2." (PMID 28351398, 2017). "As the pivotal negative regulators of cytokine signaling both in tumor cells and immunocytes, the dysregulation of the expression and function of SOCS1 and SOCS3 proteins significantly promotes tumor growth, migration, and invasion." (PMID 28228755, 2017). "Nevertheless, considering the disparity in the expression patterns of SOCS1 and SOCS3 in tumor cells and immunocytes, contradicting therapeutic approaches have been proposed." (PMID 28228755, 2017). "Subgroup meta-analysis by geographical populations was performed for p16, RASSF1A, GSTP1, APC, RUNX3, SOCS1 and PRDM2 between HCC tumor tissues and adjacent tissues." (PMID 27835605, 2016). "The meta-analysis of p14, p15, p73, APC, SOCS1, MGMT, SFRP1, PRDM2, DAPK1, RARβ, IGF2 and hMLH1 genes methylation was performed between HCC tumor tissues vs adjacent tissues and HCC tumor tissues vs normal tissues." (PMID 27835605, 2016). "SOCS1, SOCS6 and PTEN have been identified as tumor suppressors in a broad range of human malignancies, including NSCLC." (PMID 27811366, 2016). "For example, suppressor of cytokine signaling 1 (SOCS1) and tumor protein 53-induced nuclear protein 1 (TP53INP1) – two validated targets of miR-155 –have been shown to regulate tumor growth, invasion, and metastasis." (PMID 25823817, 2015). "The methylation of SOCS-1 leads to a with reduced expression of the SOCS gene, LN metastases and an advanced tumor stage." (PMID 25997695, 2015). "It was shown that miR-155 targets several tumor suppressors such as SOCS1, FOXO3, and VHL and is involved in the regulation of cell survival, growth, chemosensitivity and tumor angiogenesis." (PMID 26156018, 2015).
tumor (continued). "In contrast, when we analysed the tumours of the mice, we found high levels of the miR-155 targets SOCS1 and C/EBPβ and low pY-STAT3 levels in anti-miR-155-treated tumours, suggesting long-term target regulation." (PMID 25820993, 2015). "The suppressor of cytokine signaling-1 (SOCS-1) inhibits the signaling of the Janus kinase (JAK)/signal transducers and activators of transcription (STAT) pathway by several cytokines and has tumor suppressor activity." (PMID 25997695, 2015). "SOCS1 also controls STAT and toll-like receptor (TLR) signaling to exert a tumor suppressive function." (PMID 25893382, 2015). "Since high SOCS1 levels have been described to suppress pY-STAT3, we looked at the activity of STAT3 in these tumours." (PMID 25820993, 2015). "In our investigation we evaluated the correlation between miR-155, SOCS1 and STAT3 in 63 tumor and 21 control mucosa specimens." (PMID 23437123, 2013). "In order to investigate the SOCS1 protein expression level in LSCC, we used western blot to detect SOCS1 in 63 tumor and 21 control mucosa specimens." (PMID 23437123, 2013). "SOCS1 and IGFBP5, which were upregulated by HIF-1alpha at the mRNA level, are closely related with biological properties of tumor (as we will describe in the discussion)." (PMID 20003295, 2009). "Promoter hypermethylation in 10 tumour-related genes (APC, E-cadherin, GSTP1, hMLH1, MGMT, p15, p16, SOCS1, TIMP3 and TGF-beta RII) was determined by quantitative methylation-specific PCR (MethyLight)." (PMID 15942635, 2005). "Higher expression of SOCS-1–3 and CIS genes was evidenced in ducts enlarged by tumour cell proliferation and in the periductal reactive stroma." (PMID 12888825, 2003). "Significantly increased expression of SOCS-1–3 and CIS transcripts was also shown by quantitative in situ hybridisation within both tumour tissue and reactive stroma." (PMID 12888825, 2003). "SOCS1-mediated inhibition of JAK/STAT signaling downregulates IL-12, a key activator of cytotoxic T lymphocytes (CTLs) and NK cells, further weakening anti-tumor immunity." (PMID 40076502, 2025). "Additionally, it was suggested that miR-21 influences the tumor microenvironment by modulating antioxidant enzymes like SOD2 and GPx1, as well as signaling suppressors SOCS1 and SOCS6, thereby promoting conditions favorable for tumor growth." (PMID 41465462, 2025). "Additionally, co-deletion of SOCS1 and PTPN2 in REGNASE-1-null T cells further enhanced anti-tumour immunity by improving mitochondrial function, indicating a promising therapeutic target for cancer immunotherapies." (PMID 38581063, 2024). "Indeed, Naka and colleagues have shown that intra-tumoral delivery of SOCS1 by adenoviral vectors resulted in reduced PD-L1 expression that was correlated increased CD8+ T cell activation and improved tumor growth control." (PMID 38415248, 2024). "Silencing of SOCS1 allowed IL-6 to induce CD155 overexpression; thus, constitutive expression of SOCS1 in tumor cells prevented CD155 overexpression upon IL-6 stimulation and may account for the weak correlation found in tumors." (PMID 39596207, 2024). "SOCS1-mediated proteasomal degradation also limits various signaling pathways involving the growth factor receptor tyrosine kinase (RTK), a critical mechanism in tumor growth, e.g. in HCC." (PMID 38711523, 2024). "Meanwhile, studies have found that SOCS1‐3 and CISH regulate immune related signals, affecting lymphocyte polarization and activation of myeloid cells, which are particularly important in the tumor microenvironment." (PMID 39307915, 2024). "In addition, SOCS1 and PTPN2 were inhibited in REGNASE-1-null CD8+ T cells, resulting in robust proliferation of effective CD8+ T cells in tumours." (PMID 38581063, 2024).
tumor (continued). "Ablation of negative regulators that hinder TCR response in T cells not only promoted T cell activation but significantly enhanced T cell tumour-killing capabilities through pathways of MAPK (RASA2), ubiquitination degradation (CBLB), and JAK/STAT (SOCS1 and TCEB1)." (PMID 38581063, 2024). "Additionally, SOCS1 (suppressor of cytokine signaling 1) is a powerful inhibitor of JAK2/STAT3 signaling, however, SOCS1 is decreased in a great number of tumors and closely related to tumor angiogenesis." (PMID 37575250, 2023). "Similar to Socs1fl/flAlb-Cre mice, Socs3fl/flAlb-Cre mice developed HCC with 100% penetrance and showed more tumor nodules than Socs3fl/fl controls, confirming the non-overlapping tumor suppressor functions of SOCS1 and SOCS3." (PMID 36765862, 2023). "Even though SOCS1 and SOCS3 show close structural similarity, increased HCC development in mice lacking either SOCS1 or SOCS3 indicates their non-overlapping tumor suppressor functions." (PMID 36765862, 2023). "SOCS1 and SOCS3 function as independent tumor suppressors in hepatocytes." (PMID 36765862, 2023). "The 3B1A cell line, derived from an untreated patient, showed the highest resistance to CDDP and the highest expression of SOCS1, suggesting the presence of CDDP-DTP cells, which may emerge alongside tumor development." (PMID 37916165, 2023). "The nonresponder‐associated gene SOCS1, a regulator of the JAK/STAT pathway, acts not only as an intracellular pathway component, but also as a modulator of the tumor microenvironment." (PMID 34791836, 2022). "We found markedly reduced SOCS1 levels accompanied by increased p-STAT1 and STAT1, decreased p-STAT3, and thus an increased p-STAT1/p-STAT3 ratio in miR-155–overexpressing EO771, 4T1, and AT-3 tumor cells compared with control cells." (PMID 35925680, 2022). "Evidence indicated that SOCS1 and SOCS3 might be involved in tumor aggressiveness and radiation tolerance." (PMID 36072803, 2022). "Furthermore, FRGs, IRGs, DEGs, and genes in the blue module were intersected, and seven hub genes (JUN, TNFAIP3, NOX4, HMOX1, SOCS1, CYBB, and TFRC), related to both ferroptosis and tumor immunity, were obtained." (PMID 35174170, 2021). "Nonetheless, even though SOCS1 mRNA expression was not significantly different between tumor and normal tissues, higher transcript levels strongly correlated with patient survival, highlighting the potential prognostic utility of SOCS1 expression in HCC." (PMID 32807134, 2020). "SOCS1 expression was also not significantly affected across tumor grades, whereas SOCS3 expression was significantly reduced with increasing tumor grade." (PMID 32807134, 2020). "Similarly to miR-146a, miR-155 upregulation promotes cell proliferation, colony formation, and xenograft tumor growth in BC models by negative regulation of SOCS1 and SHIP1, leading to constitutive STAT3 activation and pro-tumor inflammation." (PMID 32793185, 2020). "In addition to SOCS-1, the induction of signal transducer and activator of transcription 3 (STAT-3) in DCs by tumour-derived factors renders DCs tolerogenic and suppresses their antitumour potency." (PMID 30717461, 2019). "Overexpression of STAT3 plays a key role in tumor proliferation, lots of studies indicated that inhibit the activation of STAT3 is beneficial for cancer treatment, so the expression of SOCS1, SOCS2 may inhibit tumor cell survival." (PMID 30787420, 2019). "Consistent with the RNA-sequencing and RT-PCR results, Chi3l1 KO mice had increased mRNA for anti-tumor immunity molecules including CTSE, TRAL, IFNγ, T-bet, Perforin, and Granzyme B, while the expression of Th1-inhibitory molecules such as Twist1 and SOCS1 was significantly reduced." (PMID 29403003, 2018).